ALB (albumin)
Diseases named in the same sentence as ALB in open-access papers (continued):
Sharing a sentence is not in itself a finding about the gene and the disease.
cancer (continued). "Because a second serum sample was obtained only from participants who developed cancer, we were unable to compare the changes in calcium and albumin among cases to those of women without cancer." (PMID 32723677, 2020). "Several systemic inflammatory response (SIR) markers, such as platelet-to-lymphocyte ratio (PLR), neutrophil-to-lymphocyte ratio (NLR), lymphocyte-to-monocyte ratio (LMR), and albumin-to-globulin ratio (AGR), have been studied and recognized as prognostic factors in various cancers." (PMID 32967632, 2020). "Cancer targeted nanoprobes were either adsorbed (AMD3100 targeting CXCR4 and Diadzein targeting Caveolin-1) or chemically crosslinked (folic acid targeting folate receptor) to the surface of the albumin nanocomposites." (PMID 33172421, 2020). "As a composite indicator based on albumin and alkaline phosphatase, the prognostic value of pretreatment AAPR in cancer could be elucidated by investigating the function of its components (albumin and alkaline phosphatase)." (PMID 33376729, 2020). "Albumin NPs can also be decorated with antibodies such as DI17E6, a monoclonal antibody directed against αv integrins, which are cell membrane-spanning matrix adhesion domains that are highly expressed in various cancer lines." (PMID 31858848, 2020). "Although the role of albumin as a prognosticator for HNSCC has been suggested previously, the role of albumin in elderly HNSCC patients is unknown so far, and it may be even more important for the more frail geriatric cancer population." (PMID 32604773, 2020). "Several systemic inflammatory response (SIR) markers, including platelet-to-lymphocyte ratio (PLR), neutrophil-to-lymphocyte ratio (NLR), lymphocyte-to-monocyte ratio (LMR), and albumin-to-globulin ratio (AGR), have emerged as prognostic markers in various cancers." (PMID 32967632, 2020). "Therefore, in the tumor intestitium, SPARC binds to albumin-bound PTX, which facilitates release of PTX near cancer cells and increases the antitumor efficacy of nab-PTX." (PMID 31783552, 2019). "Our study indicates that GPS score based on serum CRP and albumin levels may show inflammatory status; it might also have prognostic value in ICCU patients as in cancer patients." (PMID 31096693, 2019). "However, the albumin / CRP ratio, also considered as the Inflammatory-Nutritional Index (INI), is seldom reported with a prognosis of cancer." (PMID 31164099, 2019). "Although albumin has been used to determine the patient's general condition, and carcinoembryonic antigen (CEA) has been correlated with adenocarcinoma cancers and neuron-specific enolase (NSE) in epithelial cancers, they cannot be used reliably for treatment decisions." (PMID 30891428, 2019). "Higher CRP level was associated with male, higher white blood cell count, lower BMI and albumin, ever smoking, later cancer stage and non-resection." (PMID 31148582, 2019). "Albumin, therefore, is reflective of the inflammation and immune status of cancer, although it alone is not sufficient to predict the final outcome in cancer patients." (PMID 29290069, 2018). "CAR is calculated from serum albumin and CRP levels and was first developed to predict outcomes in patients with acute medical admissions, and has recently gained attention as an inflammation-based marker for predicting outcomes in cancer patients." (PMID 30034622, 2018). "However, in our subgroup analysis excluding cancer patients, the CRP/albumin ratio was also an independent predictor of 28-day mortality in the multivariate analysis." (PMID 30297655, 2018). "It was speculated that the VE-albumin core-shell nanoparticles would be a suitable drug delivery system for anticancer drug delivery to over MDR, in cancer." (PMID 30366367, 2018). "Accumulation of oxidized albumin is associated with the progression in various chronic diseases, but there is no known role for albumin oxidation in the pathophysiology of cancer." (PMID 30504805, 2018).
cancer (continued). "The negative correlation of BChE and albumin with the inflammatory markers in this study supports previous observations for cancer patients." (PMID 29113384, 2017). "In the presence of diagnosis of malignant tumor and pregnancy/childbirth, even though there was a correlation between low levels of albumin and length of stay, there was no statistical significance because of the reduced number of parameters available." (PMID 28344803, 2017). "The modified Glasgow prognostic score (mGPS) is calculated based on the serum concentrations of C-reactive protein (CRP; cutoff value: 10 mg/l) and albumin (ALB; cutoff value: 35 mg/l) levels, which focusing on systemic inflammation and nutritional status in cancer patients." (PMID 29245945, 2017). "Local blood volume in KAT-4 carcinomas, measured as the 5 min distribution volume for 125I-albumin, was not affected by treatment with imatinib." (PMID 28231806, 2017). "The combination of CRP and albumin in the GPS may reflect both the presence of a systemic inflammatory response and progressive nutritional decline in cancer patients." (PMID 26929186, 2016). "Recently, the albumin to globulin ratio (AGR), which also reflects the degree of systemic inflammation, has been reported to be a prognostic marker in patients with colorectal, lung and breast cancers." (PMID 25934494, 2015). "In addition, this study confirms previous findings that low albumin and increased CRP levels are useful markers for survival time in palliative cancer patients." (PMID 26018761, 2015). "Consequently, several biomarkers have been reported to reflect the link between inflammation and cancer, such as interferon-gamma/interleukin-4 ratio and inflammation-based prognostic score (Glasgow prognostic score) based on CRP and albumin levels." (PMID 25885254, 2015). "Retrospective clinical series on patients in Glasgow, Scotland, for whom data from the Scottish Cancer Registry, including Gleason score, Prostate Specific Antigen (PSA), C-reactive protein (CRP) and albumin, six months prior to or following the diagnosis, were included in this study." (PMID 23768149, 2013). "Hence, in this work, we have formulated the albumin- and chitosan-based hybrid nanocarrier formulation with ANC as core with surface topped positively charged chitosan layering for efficient cancer specific delivery of loaded drug." (PMID 24106715, 2013). "Previously, in large cohort studies, a number of biochemical parameters (other than C-reactive protein and albumin that compose the mGPS) including bilirubin, Alk phos, GGT and calcium, have been reported to predict overall and cancer-specific survival." (PMID 21266974, 2011). "The patients were selected on the basis that measurements of C-reactive protein, albumin and calcium had been performed and were therefore not necessarily representative of all cancer patients diagnosed and treated in the North Glasgow area." (PMID 21266974, 2011). "The strongest associations (Spearman's correlation ⩾0.3) in both the non-cancer and cancer groups were found between albumin, C-reactive protein and Alk phos, AST and ALT, AST and GGT and ALT and GGT (all P<0.001)." (PMID 20717110, 2010). "These factors were selected cancer chemotherapy agents, concentrations of the binding proteins; albumin and AAG as well as nonesterified fatty acids (NEFA)." (PMID 22615603, 2010). "In particular, C-reactive protein was associated with albumin and Alk phos and GGT associated with AST and ALT in both cancer and non-cancer cohorts." (PMID 20717110, 2010). "Our results also reveal that combining serum albumin level, serum CEA level and UICC stage could be more accurate to predict cancer-specific survival rates of CRC patients." (PMID 19691850, 2009). "Similarly, an inflammation-based score, based on two routinely measured acute phase proteins (C-reactive protein and albumin) and the Glasgow Prognostic Score (GPS) has been reported to predict the cancer-specific outcome in Dukes’ B colon cancer." (PMID 19209171, 2009).
cancer (continued). "Although the hematological results suggest an increase in WBC, which could indicate systemic inflammation, the lack of elevated levels of albumin, CRP, and IL-6 suggests that cancer did not cause systemic inflammation." (PMID 40284805, 2025). "Similarly, low serum albumin values are an established negative prognostic factor in patients with cancer and PC specifically, underscoring the reliability of our dataset to capture significant factors influencing disease progression and survival outcomes." (PMID 41375007, 2025). "Furthermore, low nutritional status and secondary anemia are frequently brought on by malignant tumors, and certain non-inflammatory markers like albumin and hemoglobin are also frequently utilized as prognostic indications for a bad prognosis for cancer." (PMID 41142623, 2025). "In this study, several materials, including bovine serum albumin (BSA), chitosan, polymethyl vinyl ether‐alt‐maleic anhydride, and tocopherol polyethylene glycol succinate, are explored to develop stable SeNPs and further evaluate their potential as candidates for cancer treatment." (PMID 39205539, 2025). "In subtype 2, the SHAP importance of ALB was greatest over the 90 days preceding death, and the involvement of inflammatory markers, such as CRP, remained minimal, indicating that the trajectory of subtype 2 represents severe malnutrition or hepatic dysfunction owing to cancer progression." (PMID 40924724, 2025). "Notably, the LDH-to-albumin ratio (LAR), which integrates metabolic inflammation and nutritional depletion, has not yet been comprehensively investigated through evidence-based frameworks in cancer research." (PMID 40693202, 2025). "There have been some other recent in vitro studies utilizing cancer cell lines of human origin, that is, HepG2 and LO2 cells, that investigated the molecular interactions of 6PPD and 6PPD-Q within cells – e.g., effects on amino acid synthesis and interactions with albumin." (PMID 40832469, 2025). "Furthermore, albumin accumulation in solid tumors due to leaky vasculature and impaired lymphatic drainage could confer particular advantages to HSA‐based strategies for cancer therapy." (PMID 38737471, 2024). "However, denatured albumin has a diminished ability to bind to GP60 or SPARC, so how to maximize the preservation of albumin activity is the key to the effective use of GP60 or SPARC for cancer therapy." (PMID 38323081, 2024). "We speculate that prealbumin may outperform albumin in assessing nutritional status, but its prognostic performance in cancer cachexia patients is not as accurate as that of albumin." (PMID 38438901, 2024). "Furthermore, the β-defensin-2-loaded human serum albumin (DF-HSA), gefitinib-loaded EVs, and triptolide prodrug-loaded UPSM (T-UPSM) are all effectively delivered into cancer cells by macropinocytosis for cancer therapy." (PMID 39000072, 2024). "Many hematological parameters have been identified as significant prognostic markers for various cancers, such as lymphocyte-to-monocyte ratio, platelet-to-lymphocyte ratio, C-reactive protein-to-albumin ratio, controlling nutritional status score (CONUT), and fibrinogen-to-albumin ratio." (PMID 39723376, 2024). "Moreover, albumin acts as a negative acute-phase reactant, with levels typically decreasing in chronic inflammatory conditions like cancer." (PMID 39195131, 2024). "The measurement of CRP and albumin that are present in the GPC showed promise in predicting complications, which is worth discussing the need to include such parameters in the staging and mandatory preoperative surgical preparation in this disease and, possibly, in all malignant neoplasms." (PMID 38985034, 2024). "The mechanisms underlying the association between lower PNI scores and worse survival in cancer patients are not yet well understood, because albumin and lymphocytes are two important factors in the PNI equation, which may explain the relationship between PNI and mortality in cancer survivors." (PMID 38455180, 2023).
cancer (continued). "The significantly overexpressed sEV proteins in the BC plasma-derived UCT isolates were ALB, COL1A1, CSN1S1, EEF1A2, and RPL3; and the C1S, C5, C7, and CFHR2 sEV proteins in the UCT isolates were the most downregulated proteins in the BC plasma compared to the non-cancer control." (PMID 37895140, 2023). "While flaxseed albumin has not been as extensively studied as other components like lignans or omega-3 fatty acids, there exists some evidence to suggest its potential anti-cancer properties." (PMID 37987317, 2023). "Moreover, this study observed that most of the cancer patients had low hemoglobin (10 ± 2.6), low albumin, and decreased urine output; however, none of these factors proved significant in determining the prognosis of acute renal damage." (PMID 38084195, 2023). "Based on the exclusion criteria, 40 patients were excluded (5 with secondary IgAN, 6 with ESRD at admission, 13 with conditions affecting albumin and fibrinogen levels, 7 with malignancies, and 9 without complete data), and 245 patients were ultimately enrolled in the analysis." (PMID 37013663, 2023). "High serum LDH and low albumin levels are historically considered as negative predictors in cancer patients, first for their role as biomarkers of cancer metabolism and second for their relationship with cancer cachexia." (PMID 38094601, 2023). "On the other hand, human serum albumin (HSA) nanoparticles could also be used as carriers for various flavonoids, including fisetin, to deliver them to specific locations, to contribute to selectively affect cancer cells." (PMID 37960338, 2023). "Albumin (ALB) and globulins (GLB), the main components of serum proteins, had been proved to involve in the development of systemic inflammation and could be widely used to assess nutritional status and disease severity in cancer patients." (PMID 37828259, 2023). "Due to the lack of sufficient serum albumin combined with drugs, if patients with cancer develop hypoproteinemia, chemotherapy drugs may have high residues in the blood and high toxicity." (PMID 37836573, 2023). "However, compared with albumin or globulin alone, the A/G ratio was not easily affected by changes in body fluids, such as hemoconcentration or hemodilution, which could be used as a more objective and stable clinical indicator to assess the risk of cancer in patients." (PMID 37495731, 2023). "Albumin is expressed as an acute-phase protein showing a negative correlation with the severity of the inflammatory response, and higher values of this protein predict longer OS in a cohort of cancer patients attending a cachexia support service." (PMID 37370816, 2023). "Furthermore, accumulating evidence has shown that nutritional and immune status, represented by the prognostic nutritional index (PNI), serum albumin, CRP, and body mass index (BMI), play a role in the development and progression of malignant tumors, which in turn affects survival." (PMID 36831069, 2023). "In addition to local inflammatory reaction, cancer patients often exhibit systemic inflammatory response, such as changes in peripheral blood cell counts and C-reactive protein (CRP), decreased hemoglobin and serum albumin (Alb) levels." (PMID 36635689, 2023). "It has been investigated whether or not albumin-based Nanomedicines could be beneficial in cancer treatment." (PMID 37007050, 2023). "In addition to serum albumin, PNI also incorporates the lymphocyte count in the peripheral blood, which is a crucial biomarker of the host’s cellular adaptive immune response against cancer cells." (PMID 37836546, 2023). "Serum albumin and total cholesterol as the main nutritional indicators not only reflect the overall nutritional status of the patient but also closely related to the prognosis of various types of cancer." (PMID 37743468, 2023).
cancer (continued). "A decreased albumin concentration may also be stimulated by a negative acute phase response secondary to inflammation or cancer cytokines, as well as possibly due to inadequate intake and absorption, increased loss or sequestration." (PMID 36699338, 2022). "In fact, though it may not have quite reached statistical significance, ΔS-Cys-Albumin was modestly elevated in every matrix from cancer patients relative to the cancer-free control donors." (PMID 36182099, 2022). "Moreover, the GPS, a cumulative inflammation-based cancer-prognostic marker composed of serum elevation of CRP and decrease in albumin concentration, is likely to reflect host systemic inflammatory response and has been reported to be significant as a prognostic indicator in cancer-bearing patients." (PMID 36587139, 2022). "Interestingly, WGS revealed that mutational clusters accumulated in ALB (encoding albumin) or APOB (encoding apolipoprotein B), although these were not directly associated with cancer development." (PMID 35158835, 2022). "This indicated that GI cancer patient serum samples tended to have slight to modestly higher ΔS-Cys-Albumin values than the cancer-free control donors regardless of any thawed-state exposure that may have occurred." (PMID 36182099, 2022). "Finally, CONUT consists of lymphocytes and albumin together with cholesterol, so it is not difficult to understand that CONUT is associated with the prognosis of cancer patients." (PMID 35571914, 2022). "Patients of GPS 2 with low serum albumin and high CRP levels may be cancer cachexia." (PMID 34519976, 2022). "Therefore, more and more inflammatory and/or nutritional predictors, such as C-reactive protein (CRP), neutrophil to lymphocyte ratio (NLR), albumin (ALB), and CRP to ALB ratio (CAR), have been applied either alone or in combination to various cancers in recent years." (PMID 34676808, 2022). "ALB and SQLE were upregulated in the “amino acid metabolism, increased albumin levels, and molecular transport” network at all time points, and actin-related protein 3B (ACTR3B) was upregulated in the “cancer, hematological disease, and immunological disease” network at all time points." (PMID 36299731, 2022). "In addition, serum albumin (ALB) is considered to be the simplest and effective factor reflecting human nutritional status and liver function, and is also the decisive factor of cancer cell immune response." (PMID 36016629, 2022). "In addition, albumin is a negative acute phase reactant, and its levels decrease in chronic inflammatory states like cancer." (PMID 36533070, 2022). "According to some reports, CRP/ALB ratio may have a prognostic value in cancer, unfortunately, we were not able to confirm this in our patient’s cohort." (PMID 35174082, 2022). "In this study, we aimed to develop a series of albumin binder-truncated Evans blue (EB) modified FAP targeted radiotracers, and optimize the pharmacokinetic (PK) characteristics to overcome the existing limitations in order to apply in the radionuclide therapy of cancer." (PMID 34987657, 2022). "In other cancers that invade the liver, measurable changes have been noted in liver function serum markers alanine transaminase (ALT), aspartate transaminase (AST), total bilirubin (TBIL), gamma glutamyltransferase (GGT), alkaline phosphatase (ALP), albumin (ALB), and carcinoembryonic antigen (CEA)." (PMID 36551674, 2022). "In addition, presence of cancer and albumin ≤ 3.0 g/dL, which were not statistically meaningful but were thought to have a relative effect on all-cause mortality, were selected." (PMID 34844565, 2021). "Moreover, a low albumin concentration reflects cancer-induced malnutrition and can have negative impact on prognosis." (PMID 34360768, 2021). "Albumin is a negative acute-phase protein that was found to decrease in response to inflammation in chronic infection, whereas high levels of globulin were reported in cancer or rheumatic diseases." (PMID 34206598, 2021).